RIPK3 (receptor interacting serine/threonine kinase 3)
Diseases named in the same sentence as RIPK3 in open-access papers (continued):
Sharing a sentence is not in itself a finding about the gene and the disease.
diabetes (9 papers, 2020 to 2025). "Pharmacological inhibition of RIPK3 reduces β cells loss in mouse model of diabetes, suggesting a potential role of necroptosis in T2D pathogenesis." (PMID 39872161, 2022). "Furthermore, Wilms tumor protein‌‌ 1 (WT1) staining demonstrated that podocyte‐specific RIPK3 KO reduced podocyte loss caused by diabetes." (PMID 40539374, 2025). "Our observations suggest that curcumin might be a potential therapeutic agent to minimize the progression of podocytopathy caused by diabetes as an inhibitor of RIPK3." (PMID 35706905, 2022). "Inhibition of RIPK1 and RIPK3 affects the developmental progression of retinopathy in animal models of diabetes." (PMID 37954576, 2023). "In mouse model of diabetes, high-fat diet induces ER stress in islets, which activates RIPK3, leading to NF-κB-mediated proinflammatory IL1β expression and β cells dysfunction and loss." (PMID 39872161, 2022). "Next, we suppressed the expression of RIPK3 by pharmacological means, and provided a basis for finding a new drug that antagonizes diabetic myocardial damage." (PMID 35805993, 2022). "Having demonstrated that both RIPK3 gene knockout and dabrafenib improved the fibrotic response induced by diabetes, we assessed the albuminuria with albumin-to-creatinine ratio (ACR)." (PMID 32591618, 2020). "Significant up-regulation of RIPK3 activity was evident in the kidney cortex of animals with diabetes." (PMID 32591618, 2020). "RIPK3 gene knockout reversed diabetes-induced type III collagen expression in the kidney cortex compared to diabetic WT mice (P < 0.0001)." (PMID 32591618, 2020). "Although further investigation is needed to clarify the specific roles of RIPK3 in islet inflammation and β-cell death, these data indicate that therapies targeting RIPK3 could protect β-cells from diabetes-relevant cytotoxic stimuli." (PMID 38842911, 2024). "There has been increasing interest in targeting significant regulators of the inflammatory pathway, notably receptor-interacting serine/threonine-kinase-1 (RIPK1) and receptor-interacting serine/threonine-kinase-3 (RIPK3), as drug targets for managing inflammation in treating diabetes complications." (PMID 37954576, 2023). "Thus, the combination of low-dose RIPK1 and RIPK3 inhibitors is an effective strategy against diabetes mellitus induced MF." (PMID 35165268, 2022). "However, genetic inactivation of RIPK3 promotes caspase-8-dependent adipocyte apoptosis and WAT inflammation, leading to impaired insulin signaling and glucose intolerance, suggesting a protective role of RIPK3 in diabetes." (PMID 39872161, 2022). "Our data support the tenet that RIPK3 may mediate diabetes-induced fibrosis through the NLRP3 inflammasome." (PMID 32591618, 2020). "Therefore, a combination of inhibitors targeting RIPK1 and RIPK3 and hypoglycemic drugs may increase effectiveness in treating diabetes mellitus." (PMID 37954576, 2023). "Third, pharmacological inhibition of RIPK3 attenuated cardiomyocyte death and cardiac pathology in a mouse model of type-1 diabetes, indicating the potential of pharmacological inhibition of necroptosis signaling as a useful therapeutic intervention for cardiac complications of diabetes." (PMID 36030201, 2022). "Although inhibition of the RIPK1-RIPK3 necrosome with the combination of low dose of RIPK1 and RIPK3 inhibitors is an effective strategy against diabetes mellitus induced MF, there are several limitations in this study that ought to be addressed." (PMID 35165268, 2022). "At 16 weeks after induction of diabetes, the mice exhibited elevated blood glucose levels, increased kidney weight, and decreased body weight, while podocyte‐specific RIPK3 KO had no impact on these indicators." (PMID 40539374, 2025). "Second, the use of a monkey model of type-1 diabetes provided translational evidence that the necroptosis signaling RIPK3 and MLKL are activated in diabetic hearts and may represent new therapeutic targets for cardiac complications of diabetes." (PMID 36030201, 2022).
diabetes (continued). "In our study, RIPK3 inhibition prevented fibrosis in diabetic nephropathy but failed to improve diabetes-induced albuminuria." (PMID 32591618, 2020). "While it is increasingly acknowledged that diabetes is an autoinflammatory condition and its complications stem from a prolonged low-grade inflammatory state, the development of drugs targeting RIPK1 and RIPK3 to alleviate diabetic complications remains inadequate." (PMID 37954576, 2023). "Since overactivation of RIPK1 and RIPK3 can lead to harmful inflammatory responses and tissue damage, understanding the precise mechanisms of RIPK1 and RIPK3 regulation of inflammation and the development of selective inhibitors are of utmost importance for the treatment of diabetes complications." (PMID 37954576, 2023). "In our study, RIPK1, RIPK3, and their phosphorylated forms were up-regulated in HGF-treated CFs and the myocardial tissues of diabetic rats, and inhibition of this pathway abrogated the pathological effects of HGF, suggesting the involvement of necroptosis in diabetes mellitus induced MF." (PMID 35165268, 2022). "However, the total protein levels of RIPK3 and MLKL were similar between sham and diabetes groups." (PMID 36030201, 2022). "However, neither RIPK3-/- or dabrafenib treated mice showed a significant reduction in diabetes-induced albuminuria." (PMID 32591618, 2020). "To investigate whether RIPK3 deficiency alleviates renal fibrogenesis, we compared WT and RIPK3 -/- mice, each with or without diabetes." (PMID 32591618, 2020).
injury (9 papers, 2019 to 2025). Damage inflicted on the body as the direct or indirect result of an external force, with or without disruption of structural continuity. "Furthermore, immunochemical staining of RIPK1, RIPK3, and MLKL showed that YQJOF reduces hepatocytic RIPK1, RIPK3, and MLKL levels, which were upregulated in chronic liver injury, acute liver injury, and ACLF model." (PMID 33967802, 2021). "In addition, dabrafenib was found to disrupt the interaction between RIPK3 and MLKL and, consequently, to reduce necroptosis in an acetaminophen-induced liver injury model." (PMID 31817643, 2019). "Unlike Nec-1s, the RIPK3 inhibitor GSK ́872 was not protective when administered prophylactically, at a dose (5 mg/kg) that was effective in a mouse model of acute lung injury." (PMID 39705008, 2025).
Lymphadenopathy (9 papers, 2015 to 2025). Enlargement (swelling) of a lymph node. "Since RIPK3 and Caspase8 double deficient mice suffer from lymphadenopathy and splenomegaly at an old age41,42, we compared Ripk1+/+, Ripk1Y383F/Y383F, Ripk3−/−Caspase8−/− and Ripk1Y383F/Y383FRipk3−/−Caspase8−/− mice side by side at a young age at 8 weeks and old age at 16 weeks." (PMID 36329033, 2022). "Due to the splenomegaly and lymphadenopathy that occurs in Casp8−/−; Mlkl−/− and Casp8−/−; Ripk3−/− mice, they were sacrificed once endpoint criteria were reached and skin samples were collected for immunohistochemical analysis." (PMID 38783091, 2024). "Lymphadenopathy was also abated in both young and aged RIPK3−/−CreLysMCasp8fl/fl mice compared with CreLysMCasp8fl/fl mice." (PMID 26471282, 2015). "We found that the lpr phenotype, characterized as lymphadenopathy and splenomegaly, became apparent in FADD−/− RIPK3−/− double knockout (DKO) mice past 3 months of age (middle)." (PMID 30867408, 2019). "RIPK3−/− mice have been previously shown to be viable and fertile, and initially were found to have no phenotype, although more recent data has shown lymphadenopathy in aging RIPK3−/− mice, over one year of age." (PMID 29540162, 2018). "While reducing apoptosis in the intestine, the rescue through haplosufficiency of TRADD did not lead to lymphadenopathy and splenomegaly in the resulting Ripk1−/−Ripk3−/−Tradd+/− mice, unlike the severe lpr-like symptom in Ripk3−/−Fadd−/− or Ripk1−/−Ripk3−/−Fadd−/− mice 29,33." (PMID 30741936, 2019). "The role of caspase-8, RIPK3, and MLKL in non-programmed cell death has been reported to regulate lymphadenopathy, lymphoproliferation and immunodeficiency." (PMID 35064213, 2022).
amyotrophic lateral sclerosis (8 papers, 2018 to 2024). Amyotrophic lateral sclerosis (ALS) is a neurodegenerative disease characterized by progressive muscular paralysis reflecting degeneration of motor neurons in the primary motor cortex, corticospinal tracts, brainstem and spinal cord. "In CNS, both RIPK1 and RIPK3 are implicated in playing a role in neurological diseases such as multiple sclerosis, amyotrophic lateral sclerosis (ALS), AD, and PD by promoting neuroinflammation, cytokine production by microglia, and astrocyte and neuronal cell death." (PMID 39057755, 2024). "Although robust expression of RIPK3 has not been detected in the healthy brain, RIPK3 has been implicated in the pathogenesis of amyotrophic lateral sclerosis as well as WNV neuropathogenesis in the brain." (PMID 36121858, 2022). "Necroptosis is a form of regulated necrotic cell death, in which RIPK1/RIPK3 kinases mediate activation of the MLKL kinase, and is emerging as a relevant pathway of cell death in other neurodegenerative conditions, such as amyotrophic lateral sclerosis." (PMID 30989755, 2019).
chronic kidney disease (8 papers, 2016 to 2026). Impairment of the renal function secondary to chronic kidney damage persisting for three or more months. "The molecular mechanisms by which RIPK1 and RIPK3 contribute to kidney fibrosis during the transition from AKI to chronic kidney disease are the subject of ongoing investigation." (PMID 39705008, 2025). "Although studies on the association between RIPK3 and chronic kidney disease (CKD) are lacking, we reported that RIPK3 played an important role in kidney fibrosis via the AKT pathway." (PMID 33513913, 2021). "From AKI to chronic kidney disease (CKD), under the regulation of IRI, the expression and interaction of RIPK3 and MLKL can induce necrosis of proximal renal tubular cells and promote the activity of inflammasome." (PMID 34977874, 2021). "Our data do not establish whether transiently inhibiting RIPK1 or RIPK3 early during the AKI to chronic kidney disease transition reduced the severity of fibrosis or merely delayed its onset." (PMID 39705008, 2025).
liver fibrosis (8 papers, 2015 to 2025). "OGT glycosylates RIPK3 and reduces the stability of the RIPK3 protein and therefore inhibits necroptosis, so that the loss of O-GlcNAc leads to liver fibrosis and inflammation due to unregulated necroptosis." (PMID 40305291, 2025). "RIPK3 deficiency alleviated liver fibrosis in a caspase-8-dependent manner by regulating JNK signaling pathway." (PMID 36114543, 2022). "Next, we determined the effect overexpressing Ripk3 on the age-related increase in liver fibrosis, which has been observed in mice." (PMID 37792157, 2023). "In A-KO mice, in addition to decreased expression of liver fibrosis-related genes, the Ripk3 and Tnf genes, as well as RIPK3 protein expression and RIPK3 and MLKL phosphorylation, were decreased compared with control mice." (PMID 36690638, 2023). "The RIPK3-dependent necroptosis resulted in liver injury, inflammation and liver fibrosis." (PMID 32824744, 2020). "The initial study of necroptosis in NAFLD showed the upregulation of RIPK3 in NASH patients and in a mouse model using the MCD diet that contributed to liver injury and liver fibrosis." (PMID 32824744, 2020). "Assessment of liver fibrosis using PSR staining that detects collagen fibers in a tissue revealed a significant increase in PSR staining in old WT mice (7.3-fold) compared to young mice, whereas Mlkl−/− or Ripk3−/− aged mice showed a significant reduction in PSR staining." (PMID 39930289, 2025).
myocardial hypertrophy (8 papers, 2016 to 2026). "However, the role of RIPK3-mediated necroptosis in myocardial hypertrophy caused by pressure overload remains largely unexplored." (PMID 37833985, 2023). "RIPK3 deficiency could ameliorate myocardial injury in mice with cardiac hypertrophy, improve cardiac function, inhibit CaMKII activation, correct CaMKIIδ alternative splicing disorder, and reduce necrosis." (PMID 37833985, 2023). "RIPK3 deficiency could ameliorate myocardial injury in mice with cardiac hypertrophy, improve cardiac function, inhibit CaMKII activation, correct the CaMKII δ alternative splicing disorder, and reduce necrosis." (PMID 36046685, 2022). "However, the role of RIPK3-mediated necroptosis in cardiac hypertrophy caused by pressure overload remains unclear." (PMID 36046685, 2022). "Xueet al. established a rat model of cardiac hypertrophy by aorticnarrowing, revealing a significant elevation in RIPK3 expression in hypertrophiedmyocardial tissues—the myocardial hypertrophy phenotype was reduced after RIPK3downregulation." (PMID 39484135, 2024). "Collectively, CaMKII activation and necroptosis were increased in myocardial hypertrophy in an RIPK3-dependent manner." (PMID 37833985, 2023). "The cross-sectional area of mouse cardiomyocytes was observed using WGA staining, proving that both WT and RIPK3−/− mice developed cardiac hypertrophy after TAC surgery." (PMID 37833985, 2023). "Western blotting analysis showed that the expressions of RIPK1 and phosphorylated MLKL in the myocardium of RIPK3−/− mice with myocardial hypertrophy were significantly lower compared with WT mice." (PMID 37833985, 2023). "In mice with cardiac hypertrophy, the expression of RIPK3 downstream protein RIPK1 and the phosphorylation of MLKL were inhibited, and meanwhile, apoptosis was improved." (PMID 37833985, 2023). "Our study found that the expression of RIPK3 in the myocardial tissue of mice with myocardial hypertrophy was significantly increased." (PMID 37833985, 2023). "Through Sirius red and Masson staining, we found that after interfering with RIPK3, myocardial collagen deposition in mice with myocardial hypertrophy was reduced, and myocardial fibrosis was improved." (PMID 37833985, 2023). "H&E staining showed that depletion of RIPK3 alleviated the distortion and arrangement disorder of cardiomyocytes in mice with cardiac hypertrophy." (PMID 37833985, 2023). "Given that RIPK3 was a key signaling molecule in the pathways related to necroptosis, we studied the differences in cardiac hypertrophy between WT mice and RIPK3−/− mice." (PMID 37833985, 2023). "Western blotting analysis showed that the expressions of ASF and SC-35 in the myocardium of RIPK3−/− mice with myocardial hypertrophy were significantly lower compared with WT mice." (PMID 37833985, 2023). "Further, DHE staining and transmission electron microscopy, respectively, showed that after the interference of RIPK3, the oxidative stress level and the abnormalities of mitochondrial ultrastructure in mice with myocardial hypertrophy were corrected." (PMID 37833985, 2023). "Our study found that in WT mice with myocardial hypertrophy, the phosphorylation and oxidation of CaMKII were significantly enhanced, while these conditions were significantly reversed in RIPK3−/− mice." (PMID 37833985, 2023). "Intraperitoneal injections of RIPK3 inhibitors were given to the WT mouse and extensive examination of hypertrophic cardiac features were performed to explore the effect of RIPK3 deletion and downregulation on myocardial hypertrophy." (PMID 36046685, 2022). "It is suggested that both RIPK3 gene knockout and RIPK3 inhibition can correct the CaMKII δ alternative splicing disorder in myocardial tissue of myocardial hypertrophy mice, and their regulatory effects are consistent." (PMID 36046685, 2022).
myocardial hypertrophy (continued). "Given that RIPK3 is a key signaling molecule in necroptosis-related pathways, the present study compared the differences in cardiac hypertrophy presentation between WT mice and RIPK3−/− mice and mice treated with the RIPK3 inhibitor GSK'872." (PMID 36046685, 2022). "Collectively, CaMKII activation and necrosis were increased in myocardial hypertrophy in an RIPK3-dependent manner." (PMID 36046685, 2022). "The study presented herein identified that the phosphorylation and oxidation of CaMKII were significantly upregulated in WT mice with cardiac hypertrophy, but were significantly reduced in RIPK3−/− mice." (PMID 36046685, 2022). "Overall, CaMKII activity and enhanced necroptosis in cardiac hypertrophy are dependent on RIPK3; the RIPK3 inhibitor GSK'872 had a significant protective effect on AMP-AngII-induced cardiac hypertrophy in WT mice." (PMID 36046685, 2022). "It is suggested that both RIPK3 gene knockout and RIPK3 inhibition can consistently improve the level of oxidative stress in myocardial tissue of myocardial hypertrophy mice and reverse the disorder of mitochondrial ultrastructure." (PMID 36046685, 2022). "Depletion of RIPK3 improved myocardial injury in mice with cardiac hypertrophy." (PMID 37833985, 2023). "We also tried to prove that silencing and down-regulation of RIPK3 could regulate CaMKIIδ alternative splicing and CaMKII activity to delay the pathogenesis of cardiac hypertrophy." (PMID 37833985, 2023). "Therefore, in the present study, we aimed to explore the role and mechanism of RIPK3-mediated necroptosis in pressure overload-induced cardiac hypertrophy." (PMID 37833985, 2023). "Taken together, these findings showed that interference with RIPK3 could indeed prevent myocardial damage in mice with myocardial hypertrophy." (PMID 37833985, 2023). "We used RIPK3−/− mice to verify the role of RIPK3 in the development of myocardial hypertrophy." (PMID 37833985, 2023). "Our results showed that depletion of RIPK3 could attenuate the oxidation and phosphorylation of CaMKII in the myocardium of mice with myocardial hypertrophy." (PMID 37833985, 2023). "In summary, the CaMKII signaling pathway might be the downstream or substrate of RIPK3 in myocardial hypertrophy." (PMID 37833985, 2023). "Therefore, in this study, we studied the mechanism by which the RIPK3 inhibitor GSK'872 had a protective effect on myocardial hypertrophy by the regulation of CaMKII." (PMID 36046685, 2022). "It is therefore likely that the CaMKII signaling pathway may be downstream of or a substrate for RIPK3 in cardiac hypertrophy." (PMID 36046685, 2022). "The present study demonstrated that CaMKII activation and necroptosis augment cardiac hypertrophy in a RIPK3-dependent manner, which may provide therapeutic strategies for HCM." (PMID 36046685, 2022). "In doing so, we attempted to demonstrate consistency between the effects of knockout of the RIPK3 gene and administration of an RIPK3 inhibitor and reveal the efficacy of RIPK3 inhibitors in reducing myocardial damage, improving cardiac function in cardiac hypertrophy." (PMID 36046685, 2022). "RIPK3 inhibitor GSK'872 has a protective effect on cardiac hypertrophy and could be an efficacious targeted medicine for HCM in clinical treatment." (PMID 36046685, 2022). "Knockdown of RIPK1 or RIPK3 by siRNA suppressed the PA-induced myocardial hypertrophy." (PMID 27057269, 2016). "A study investigating the role of RIPK3 in cardiovascular failure in a model of MI with permanent coronary artery blockage showed that knockdown of RIPK3 attenuated unfavorable cardiac remodeling, dysfunctional cardiac hypertrophy, and inflammatory reactions after MI." (PMID 38684668, 2024). "Through the tail vein injection of RIPK3−/− mice and wild-type (WT) mice with RIPK3 shRNA recombinant adeno-associated virus (AAV), transverse aortic constriction (TAC) surgery was performed to explore the effects of RIPK3 deficiency and down-regulation on myocardial hypertrophy." (PMID 37833985, 2023).